IL33 (interleukin 33)
Diseases named in the same sentence as IL33 in open-access papers (continued):
Sharing a sentence is not in itself a finding about the gene and the disease.
asthma (continued). "The importance of the alarmins, to include TSLP, IL-25 and IL-33, is that they are constitutively expressed by epithelial cells, and once released, activate Th2 cells and ILC2 responses in multiple allergic conditions and asthma." (PMID 40821845, 2025). "The IL-33/ST2 axis plays a major role in allergic reactions, particularly in asthma." (PMID 41087719, 2025). "This IL-33/ST2 signaling pathway is key in promoting allergic inflammation, including the activation of mast cells, eosinophils, and other immune cells, contributing to the inflammatory cascade in diseases like asthma and atopic dermatitis." (PMID 41012490, 2025). "According to the DrugBank database, multiple drugs targeting IL-13 and IL-33, or carried by FABP3 to the heart, have been developed and either approved or are under investigation for conditions such as atopic dermatitis, asthma, chronic obstructive pulmonary disease and bacterial growth." (PMID 41391830, 2025). "IL-33 binds to IL-1 receptor appendages on a variety of cells through long-form serum stimulating factor-2 (ST2) and activates mouse and human ILC2s, leading to the development and aggravation of asthma and AD." (PMID 40236701, 2025). "Filaggrin deficiency, known in AD, may also promote Th2 inflammation in airways by affecting E‐cadherin expression and enhancing IL‐33/TSLP release, potentially contributing to asthma." (PMID 40679787, 2025). "Patients with asthma who had higher capsaicin cough sensitivity, as well as those with functional dyspepsia, showed significantly higher sputum IL-33 levels compared to those without these features." (PMID 40863432, 2025). "Tozorakimab, an anti-IL-33 antibody developed by AstraZeneca, is currently being tested in phase 2a asthma patients, but the results are not yet available." (PMID 41145900, 2025). "A study has demonstrated that IL-33 can regulate mast cell function in many ways after binding to ST2 on the surface of mast cells, and mast cells are key effector cells of allergic airway inflammation in patients with asthma." (PMID 39925809, 2025). "Tozorakimab (anti-IL-33) is a monoclonal antibody studied in phase IIa clinical trial (FRONTIER-3) that is administered subcutaneously at a dose of 600 mg every 4 weeks, with potential benefits for early-onset eosinophilic (>300/μL) moderate-to-severe asthma." (PMID 40364184, 2025). "In recent years, the role of ILC2 in the pathogenesis of T2 asthma has been clarified with evidence of the triggering effect of thymic stromal lymphopoietin (TSLP) and IL-33, which have been correlated with more severe asthma, as well as glucocorticoid resistance." (PMID 40364184, 2025). "For the clinical context, IL-33/ST2 axis therapies, including itepekimab (anti-IL-33), astegolimab (anti-ST2), and tozorakimab (anti-IL-33), have demonstrated favourable safety profiles in phase II–III trials for asthma and COPD, supporting feasibility for oncology testing." (PMID 41284319, 2025). "Single blockade of TSLP, IL-25, or IL-33, which stimulate ILC2 and Th2 cells to release type 2 cytokines, decreases airway inflammation and hyperresponsiveness in murine asthma models, and concurrent blockade of all three cytokines produces more pronounced effects." (PMID 39962262, 2025). "Moreover, a disrupted airway epithelium drives inflammation in asthma, promoting AHR through the secretion of alarmin cytokines such as thymic stromal lymphopoietin (TSLP), IL-25, and IL-33." (PMID 39199248, 2024). "Although mast cells are mainly associated with proinflammatory biological effects, the murine chymase mMCP-4 has been shown to have protective properties in experimental asthma, dampening AHR and eosinophilic inflammation, possibly by degrading IL-33, which is a cytokine driving type 2 inflammation." (PMID 38578780, 2024).
asthma (continued). "These cell‐based data suggest that the airway microenvironment, which drives the formation of different IL33 isoforms, in combination with IL1RL1 nonsynonymous genetic variation, may determine the inflammatory response in specific asthma patients." (PMID 39301832, 2024). "Truncations of HpARI2 which lack the large loop from CCP3 are not able to block IL-33-mediated signalling in a cell-based assay and in an in vivo female mouse model of asthma." (PMID 38890291, 2024). "The released IL-33 activates various immune cells, including neutrophils, eosinophils, basophils, and T cells, a process reported to drive the pathology of pulmonary diseases, including COPD, IPF, and asthma." (PMID 39765899, 2024). "Together, the activation of TLRs, RLRs, and the IL-33/ST2 pathway by respiratory pathogens service as a critical mechanism driving alarmin production and the T2 inflammatory response in asthma, emphasizing the need for further research into therapeutic strategies aimed at modulating these pathways." (PMID 39457624, 2024). "Studies that integrate the combined effect of TSLP and IL-33 genotypes in relation to circulating cytokine levels and asthma are lacking." (PMID 38731070, 2024). "The interaction analysis showed that combination of both asthma and obesity had significant effects on IL-5, IL-10, IL-17A, IL-33, TNF-α, and leptin, but the effects were not synergistic or additive." (PMID 39902293, 2024). "Indeed, initial clinical trials targeting IL-33 using Itepekimab or TSLP through the application of Tezepelumab show promising clinical results by reducing asthma symptoms." (PMID 39497825, 2024). "Mediators including alarmins (IL-25, IL-33, TSLP) and OX40L have overlap between T2 and non-T2 inflammation and may signify unique pathways of asthma inflammation." (PMID 39194521, 2024). "Hence, instead of blocking downstream type 2 signature cytokines, the targeting of upstream alarmins, including IL-33 and TSLP has been proposed as an alternative treatment strategy for asthma and type 2 immunopathologies." (PMID 39497825, 2024). "This herb targets the IL-33/TSLP signaling pathway and significantly lowers the levels of these cytokines in the nasal and bronchoalveolar lavage fluids of mice modeling allergic rhinitis and asthma." (PMID 38931338, 2024). "However, alarmins, including IL-25, IL-33, and TSLP, derived from airway epithelial cells, have received increasing focus as upstream targets to block initial type 2 reactions and improve asthma control." (PMID 39200943, 2024). "The IL-33/CD146 axis influences EMT in asthma, with HDM extract boosting IL-33 and CD146." (PMID 38891935, 2024). "Indeed, inhibition of IL-33 and its receptor ST2 have both shown preliminary efficacy for treatment of patients with asthma and for patients with COPD." (PMID 39694589, 2024). "Physiologically relevant concentrations of IL-33 can activate the MAPK pathway, enhancing cytokine expression in human NK cells, which may influence disease outcomes in conditions like asthma and COPD." (PMID 39301028, 2024). "Mast cells play a key role in asthma pathophysiology and airway remodelling through the release of a plethora of cytokines (e.g. TSLP, IL-33, IL-25, IL-4, IL-13 and TGF-β) and angiogenic factors (e.g. VEGF-A), as well as other inflammatory mediators and bronchoconstrictors." (PMID 38609094, 2024). "Alarmins such as IL-25, IL-33 and TSLP function at the initial stages of the allergy cascade and are anticipated to have a more comprehensive impact on airway inflammation, potentially offer more effective asthma management than currently therapies." (PMID 39717777, 2024). "Therefore, targeting the inhibition of ILC2 activation by the IL-33/ST2 pathway prevents asthma, which is of great significance for studying therapeutic strategies for asthma." (PMID 38650035, 2024). "Serum IL-33 levels were also elevated in asthma patients, while TSLP showed a non-significant trend." (PMID 38731070, 2024).
asthma (continued). "They play a key role in the development of allergic disorders such as asthma, allergic rhinitis, and atopic dermatitis because they are quickly activated by TSLP, IL-33, and IL25, and they release large quantities of traditional Th2 cytokines IL-4, IL-5, IL-9, and IL-13." (PMID 38931338, 2024). "IL‐33 mRNA expression was not elevated in asthma whereas the expression of mRNA for IL1RL1, the IL‐33 receptor, was up‐regulated in the sputum of severe eosinophilic asthma." (PMID 35986608, 2023). "IL-33 production induces IL-13 production in ILC-2 cells, and TH2 cytokine-producing cells promote allergic inflammation in the experimental animal models of asthma and atopic dermatitis." (PMID 37685567, 2023). "There was no significant enrichment of any IL‐33‐activated signatures in bronchial and nasal brushings or bronchial biopsies when analysed according to asthma severity or granulocyte phenotype." (PMID 35986608, 2023). "We hypothesized that the IL-33/ST2 axis plays a role in kidney tissues in MCD, similar to that in the endobronchial tissue of asthma patients." (PMID 37907612, 2023). "When EETs were exogenously injected into a mouse model of asthma, epithelium-derived cytokine levels (including IL-1α, IL-1β, Chemokine ligand 1 [CXCL-1], CCL24, IL-33, and TSLP) were found to be significantly increased in mouse bronchoalveolar lavage fluid (BALF)." (PMID 37752512, 2023). "ILC2s produce a large amount of IL-5 and IL-13 in response to epithelial-cell-derived cytokines, such as IL-25, IL-33, and thymic stromal lymphopoietin (TSLP), which are considered to play an essential role in the pathogenesis of allergic disorders, including asthma." (PMID 37371472, 2023). "IL-33 can also be induced to be expressed and further increased in response to cellular stress or inflammation, such as in the intestinal epithelium of bone marrow transplant recipients with GVHD, asthma or COPD." (PMID 37153553, 2023). "IL-33 and ILC2 are involved in the pathogenesis of asthma and EGPA." (PMID 37179316, 2023). "IL-33 and HMGB1 have a significant role in Th2 inflammation and severe asthma." (PMID 36675299, 2023). "Asthma severity and granulocyte status did not alter IL‐33 mRNA expression except in bronchial brushings where it was significantly suppressed (p < 0.01) with respect to HC." (PMID 35986608, 2023). "In a murine model of asthma, protease allergens—such as papain and house dust mites (HDM)—and Aspergillus fumigatus damaged airway epithelial cells, releasing epithelial-derived cytokines such as IL-25, IL-33, and TSLP." (PMID 37371472, 2023). "In conclusion, through the NF-κB and MAPK pathways and histone modification, LTRAs increased IL25, IL33, and TSLP mRNA expression in lung and bronchial epithelial cells, which might provide support for the decreased effectiveness of LTRAs in asthma therapy." (PMID 36674744, 2023). "Indeed, in our hands, SARS-CoV-2 infection alone led to an increased release of inflammasome-dependent and independent proinflammatory cytokines such as IL-18 and IL-33, respectively, as well as to the decrease of anti-viral CCL4 in controls and in asthma." (PMID 37087523, 2023). "Several cytokines, including interleukin (IL)-4, IL-5, IL-13, IL-25, and IL-33, thymic stromal lymphopoietin (TSLP), and cells such as innate lymphoid cells type 2 (ILC2s), play crucial roles in orchestrating the inflammatory response in asthma." (PMID 37765327, 2023). "Epithelium-derived cytokines, including interleukin (IL)-25, IL-33, and thymic stromal lymphopoietin (TSLP), are major immune mediators secreted by epithelial cells that contribute to type 2 immune responses and the development of asthma." (PMID 36674744, 2023). "Proof-of-concept is provided in clinical studies with the IL-33 antibody etokimab, and with the ST2 antibody astegolimab showing improvement in patients with atopic dermatitis, a peanut allergy, or severe asthma." (PMID 35409061, 2022).
asthma (continued). "Although previous smaller studies have suggested potential eQTLs for IL33 and TSLP44, our eQTL analyses were sufficiently powered to identify strong airway epithelial eQTLs for both genes, which were highly co-localized with asthma GWAS signals." (PMID 35347136, 2022). "Besides, we found a positive correlation between BIRC3 and IL-10, IL-33, and TSLP in induced sputum of asthma (p < 0.05)." (PMID 35287655, 2022). "The expression of IL-33, IL-25, and TSLP should be higher in ABPA and asthma theoretically." (PMID 35983066, 2022). "Studies indicate that IL-25, like IL-33 and TSLP, has a prime position in promoting T2 asthma." (PMID 36311787, 2022). "Among the investigational anti-IL-33 mAbs, only itepekimab, but not etokimab and melrilimab, effectively improved asthma outcomes compared to PCB, but generally there was no further improvement observed when itepekimab was combined with dupilumab." (PMID 36140430, 2022). "Interleukin (IL) -5 levels were significantly higher in patients with ABPA than in those with CPA, and IL-33 and tumor necrosis factor (TNF) levels were significantly higher in patients with CPA than in those with asthma (p < 0.05, Dunn’s multiple comparison test)." (PMID 35628692, 2022). "Although IL33- and IL25-induced iNKT cell activation has been shown to play an essential role in a mouse model of asthma, it remains unclear whether CD1d-restricted NKT cells stimulated by IL33 and IL25 contribute to AD progression." (PMID 36119077, 2022). "IL33 and thymic stromal lymphopoietin (TSLP) are cytokines functioning as alarmins that are released by the airway epithelium in response to viruses, allergens and other triggers and drive type 2 responses in asthma." (PMID 36685501, 2022). "IL-33 signaling via the ST2 receptor increases inflammation in many auto/inflammatory diseases such as rheumatoid arthritis, inflammatory bowel disease, Sjögren’s disease, and asthma." (PMID 36741845, 2022). "Thus, several studies reported that both the IL-33 levels and ILC2 frequencies in the peripheral blood and lung lavage fluid of asthma patients correlate negatively with lung function as well as with each other." (PMID 36466877, 2022). "Previous studies have shown that IL-33/ST2 signaling is involved in the occurrence and development of various inflammatory and allergic diseases, including rheumatoid arthritis, inflammatory bowel disease, food allergy, and asthma." (PMID 35633657, 2022). "MUC5B, ORMDL3, MUC5AC, CHI3L1, CLCA1, and IL-33 displayed a high non-specific relationship with allergic and nonallergic asthma." (PMID 33936056, 2021). "Four independent cohorts [Lifelines, Dutch Asthma GWAS (DAG), Genetics of Asthma Severity and Phenotypes (GASP), Manchester Asthma and Allergy Study (MAAS)] and resequencing data have shown that IL-33 genetic signals potentially contribute to severe phenotypes in asthma." (PMID 34484177, 2021). "Viruses trigger asthma exacerbations by damaging or necrotizing airway cells leading to the release of airway epithelial cell-derived cytokines, like thymic stromal lymphopoietin (TSLP), IL-25 and IL-33." (PMID 34266437, 2021). "Rapidly after that, other mechanisms come into play in viral-induced asthma exacerbations, and IL-33 does not influence inflammation and recruitment of immune cell populations in the lung to the same magnitude." (PMID 34960788, 2021). "Here, in a different cohort of asthmatic patients, using ELISA and qPCR, we found that airway expression of IL-25 and TSLP, but not IL-33, was elevated in type 2–high asthma patients." (PMID 33945508, 2021). "Together, these studies suggest that the CD39–extracellular ATP axis may regulate IL-25, IL-33, and TSLP in asthma." (PMID 33945508, 2021). "Previous publications have demonstrated that the IL-33/ST2 signaling axis was involved in the occurrence and development of inflammatory and allergic diseases including rheumatoid arthritis, inflammatory bowel disease, SLE, food allergy, and asthma." (PMID 34194284, 2021).
asthma (continued). "Our results suggested that IL-33/ST2 pathway is mediated the RSV-induced acute bronchiolitis and maybe the potential targets for the prevention of asthma after acute bronchiolitis in infants." (PMID 34395633, 2021). "Our data suggest that airway expression of IL-25 and TSLP, but not IL-33, is elevated in type 2–high asthma." (PMID 33945508, 2021). "Moreover, the intensity of inflammation is higher in patients with obstructive lung diseases in our study, especially observed for IL-6 in COPD and IL-8 in both asthma and COPD, and include other mediators e.g., TSLP and IL-33 in asthma." (PMID 34168212, 2021). "The role of IL-33 in patients with chronic obstructive pulmonary disease (COPD) has not been well elucidated compared to that in patients with asthma." (PMID 33722239, 2021). "The numbers of inflammatory cells and the levels of T2 cytokines (IL-4, IL-5, IL-13, and IL-33) in BALF were increased in the LTE4-alone, OEA-alone, and LTE4-pretreated groups, and these factors play important roles in airway inflammation and asthma remodeling." (PMID 34079051, 2021). "In asthma mice models, exposure to the allergen house dust mite (HDM) prior to IAV infection led to suppression of Th1-like innate and adaptive antiviral responses as well as cytotoxic responses in response to IL-33." (PMID 34960788, 2021). "The anti-IL-33 biologic on its own was able to improve asthma control and lung function, but this was not synergistic when combined with dupilumab." (PMID 35126131, 2021). "Nevertheless, there is no obvious alleviation of airway inflammation in the HDM-induced asthma mice treated with IL-33 antibody, which might because the airway inflammation induced by HDM had basically formed when the IL-33 antibody was administrated." (PMID 34254951, 2021). "In asthma mice models, exposure to the allergen house dust mite (HDM) prior to IAV infection also led to suppression of Th1-like innate and adaptive antiviral responses as well as cytotoxic responses in response to IL-33." (PMID 34960788, 2021). "ILC2s do not depend on T cells and secrete a large number of type 2 cytokines (such as IL-4, IL5, IL-9, and IL-13) under the function of IL-25, IL-33 and thymic stromal lymphopoietin (TSLP) to participate in asthma, virus infection and worm-host defense related with the type 2 immune response." (PMID 33514798, 2021). "We found that co-culture with epithelium and moMφs significantly increased TSLP mRNA in the asthma group and to a lesser extent or did not change IL-33 and IL-17A mRNA expression in moDCs." (PMID 32842623, 2020). "The recently identified H. polygyrus alarmin release inhibitor (HpARI) binds to active IL-33 preventing its interaction with ST2 both in murine and human models, and could provide novel therapeutic options in Th2 dominated disease, such as asthma." (PMID 32983184, 2020). "Although Tezepermab, a biologic that targets TSLP for treatment, was reported to reduce the frequency of asthma exacerbations, the role of ILCS2, including IL25 and IL-33, is not fully understood, and we need to elucidate the full mechanism of its production and develop new treatment options." (PMID 32823491, 2020). "Since IL-33 is an important asthma mediator we tested whether CPL302-253 blocks this cytokine production in epithelial and T cell co-cultures, where CD8 lymphocytes induce IL-33 expression by A549 cells." (PMID 32702053, 2020). "In the context of IL-33-induced asthma, we found that mice lacking ICAM-1 developed lower AHR and lung inflammation, and confirmed our results using a clinically proven anti-ICAM-1 blocking antibody in Rag−/− mice." (PMID 33193309, 2020). "Moreover, vaccination against IL-33 reduced airway eosinophilia and airway hyperresponsiveness in a mouse model of HDM-induced asthma, propose IL-33 as a promising target for asthma intervention." (PMID 32582171, 2020).